CAV1 (caveolin 1)
Diseases named in the same sentence as CAV1 in open-access papers (continued):
Sharing a sentence is not in itself a finding about the gene and the disease.
pulmonary fibrosis (continued). "Cav-1 expression is significantly decreased in the fibrotic area, which appears as increased expression of alpha smooth muscle actin (α-SMA), a hallmark of lung fibrosis, in alveoli after bleomycin administration for 21 days, compared to control mice." (PMID 31873099, 2019). "Although others have reported that Cav-1 expression is reduced in samples of both experimental animal models of pulmonary fibrosis and patients with IPF26,28,33, we determined in which cell type Cav-1 was altered in our bleomycin-mediated pulmonary fibrosis mouse model." (PMID 31873099, 2019). "However, a substantial literature shows that Cav-1 regulates fibrosis in lung and dermal patient-derived cells and in the mouse model of bleomycin-induced pulmonary fibrosis." (PMID 29250058, 2017). "Subsequent investigation demonstrated that CAV1 protein and gene expression were markedly decreased in affected tissues from patients with SSc and idiopathic pulmonary fibrosis, and that restoration of CAV1 functional domains corrected the profibrotic phenotype." (PMID 27077889, 2016). "In addition, we demonstrated that miR-199a-5p is a key effector of TGFβ signaling in lung fibroblasts by regulating CAV1, a critical mediator of pulmonary fibrosis." (PMID 23459460, 2013). "In lung fibroblasts, miR-199a-5p acts as an effector of TGFβ signaling, regulates CAV1 expression, a critical mediator of the lung fibrosis process and participates to multiple fibrogenic associated-processes including cell proliferation, migration, invasion and differentiation into myofibroblasts." (PMID 23459460, 2013). "Gene disruption of caveolin-1, which is known to be involved in integrin clustering and activation, results in pulmonary fibrosis and impairment in liver regeneration after partial hepatectomy which was reversible by treatment with glucose, indicating the probable importance of energy preservation." (PMID 22505883, 2012). "Subsequently, studies of the role of Cav-1 in pulmonary fibrosis in humans were conducted." (PMID 22040717, 2011). "This could explain why African American patients have a higher susceptibility to developing SSc‐ILD compared to Caucasians, highlighting Cav‐1's role in promoting pulmonary fibrosis by regulating signaling pathways, cell migration, and fibroblast differentiation." (PMID 40778471, 2025). "By searching the 18 candidate hub genes in GeneCards database, we found that CAV1 and PECAM1 were specifically expressed in lung tissues, BMP4 and VEGFA were related to angiogenesis, FYN and SPP1 were related to immunity or inflammation, and COL1A1 was closely associated with pulmonary fibrosis." (PMID 37794454, 2023). "Among those genes, we found that CAV1 and PECAM1 were specifically expressed in lung tissues, BMP4 and VEGFA were related to angiogenesis, FYN and SPP1 were related to immunity or inflammation, and COL1A1 was closely associated with pulmonary fibrosis according to the GeneCards database." (PMID 37794454, 2023). "Furthermore, low caveolin-1 expression accompanied by increased IL-1β and caspase-1 has been reported in alveolar epithelial type I cells from bleomycin-injured mouse lungs and in lung sections from patients with idiopathic pulmonary fibrosis." (PMID 34698188, 2021). "It has been demonstrated, for example, that the use of prednisone slowed the progression of lung fibrosis in rats, and that the mechanism of action could be related to increased levels of Cav-1, reduction in tumor necrosis factor (TNF-α), TGF-β, and platelet-derived growth factor (PDGF)." (PMID 35008594, 2021). "Thus, the exact nature and mechanism of Cav-1’s role in pulmonary fibrosis remain open." (PMID 31873099, 2019).
pulmonary fibrosis (continued). "Therefore, treatments that increase expression of Cav-1 should be beneficial in pulmonary fibrosis." (PMID 31873099, 2019). "However, the role of Cav-1 expression in pirfenidone-treated idiopathic pulmonary fibrosis (IPF) is unknown." (PMID 27937011, 2017). "The progression of pulmonary fibrosis can be slowed down by regulating EMT through Bach1, ZEB1, NDRG1, erastin, liproxstatin-1, Cav-1 and other ferroptosis-related genes or proteins." (PMID 36672671, 2023). "The study also showed Cav1, a highly expressed membrane protein in the lungs, is downregulated in BLM-induced pulmonary fibrosis." (PMID 35083615, 2022). "Lastly, exogenous Cav‐1 peptide injection effectively upregulated Cav‐1 levels, therapeutically influenced myocardial remodelling, BLM‐induced pulmonary fibrosis and LPS‐induced inflammation." (PMID 34889029, 2022). "The present work corroborates the literature, having seen the decreased immunoexpression of Cav-1 and the increased TGF-β1 in the COVID-19 samples compared to the CONTROL group, culminating in terminal lung fibrosis." (PMID 35008594, 2021). "CAV1, NOS2, GDF15, and CDKN2A were demonstrated to be influencing the development of pulmonary fibrosis by regulating ferroptosis." (PMID 35069688, 2021). "In vitro models of lung fibrosis have demonstrated that the anti-fibrotic effects observed are regulated by TGF-β1 via ERK and JNK activation, which are mediated by Cav-1." (PMID 28970796, 2017). "Our data are in accordance with previous studies implying an interaction between Cav-1 and TGF-β1 in pulmonary fibrosis." (PMID 26881215, 2016). "Cav1 modulates SMAD2 and SMAD3 nuclear accumulation in fibroblasts in an experimental model of idiopathic pulmonary fibrosis." (PMID 25550395, 2015). "In patients with idiopathic pulmonary fibrosis (IPF), Cav-1 mRNA expression was found to be reduced in epithelial cells and fibroblasts." (PMID 22040717, 2011). "In the absence of Cav1, increased cardiac fibrosis and pulmonary fibrosis has been reported in animal models." (PMID 38926892, 2024). "Caveolin 1 has been found to prevent bleomycin-induced fibrosis by inhibiting inflammasome activation, although the roles of Cavin2 and Ehd2 in pulmonary fibrosis are not well-defined." (PMID 37852965, 2023). "Several of these genes (PELI1, MAP3K8, LAMA3, EMP2, CTNNAL1, CAV1, LRRK2, SFRP4) may also be involved in lung fibrosis, a severe complication of COVID-19." (PMID 37561814, 2023). "CAV1, NOS2, GDF15, CDKN2A may influence the development of pulmonary fibrosis by regulating ferroptosis." (PMID 35069688, 2021). "In this sense, the present study evaluated the histopathological features and immunohistochemical biomarkers (ACE-2, AKT-1, Caveolin-1, CD44v6, IL-4, MMP-9, α-SMA, Sphingosine-1, and TGF-β1 tissue expression) involved in the TGF-β1 signaling pathways and pulmonary fibrosis." (PMID 35008594, 2021). "In conclusion, pirfenidone, prednisone and acetylcysteine can inhibit airsacculitis and pulmonary fibrosis in rat IPF models, and its mechanisms may be related with enhanced caveolin-1, reduced TNF-α, TGF-β1, PDGF." (PMID 27937011, 2017). "Discussion and conclusion: Pirfenidone, prednisone and acetylcysteine can inhibit airsacculitis and pulmonary fibrosis in rat IPF models, which may be related with enhanced caveolin-1, reduced TNF-α, TGF-β1, PDGF." (PMID 27937011, 2017). "We recently reported that: (i) Cav2−/− mice, with normal levels of cav1, develop lung fibrosis over time and (ii) cav2, not cav1 drives the fibrotic process." (PMID 28352235, 2017).
pulmonary fibrosis (continued). "The current in vitro PCLS model revealed several differences to experimental animal models of chronic injury, where during the course of disease, for example in pulmonary fibrosis, a number of AEC I specific proteins are strongly diminished: T1α, ICAM-1, aquaporin-5, RAGE and Cav-1." (PMID 25635824, 2015). "We previously demonstrated that those cells of abnormal re-epithelialization were characterized by diminishment of caveolin-1 and the increased expression of matrix metalloproteinases (MMPs) and extracellular matrix metalloproteinase inducer (EMMPRIN) in lung fibrosis." (PMID 21190578, 2010). "In recent years, studies have found that Cav-1 plays an important role in the occurrence and development of respiratory diseases such as chronic obstructive pulmonary disease (COPD), hyperoxia induced lung injury, and pulmonary fibrosis by participating in autophagy of lung epithelial cells." (PMID 41030451, 2025). "Moreover, quercetin is reported to reverse the resistance to death ligand-induced apoptosis in mice model by promoting Fas Ligand receptor and caveolin-1 expression and inhibiting AKT activation, alleviating the progression of bleomycin-induced pulmonary fibrosis." (PMID 36605402, 2022). "However, ATI cells express some important anti-fibrotic factors such as caveolin-1, which is involved in FN turnover, and mice lacking caveolin-1 or −2 develop spontaneous lung fibrosis." (PMID 24891877, 2014).
colon carcinoma (61 papers, 2002 to 2025). "Altogether, bioinformatics analysis puts ezrin and caveolin-1 forward as highly ranked proteins significantly associated with vemurafenib resistance in colon cancer cells." (PMID 37629086, 2023). "Its encoded protein, c-MYC, regulates CAV1 and both promote tumour progression in prostate and colon cancer." (PMID 27852311, 2016). "In this study, we focused on the functional role of caveolin-1 in chemotherapeutic-induced apoptosis of colon cancer cells and the underlying molecular mechanism." (PMID 22745744, 2012). "Overexpression of caveolin-1 was linked to drug-resistance of cancer cells, including colon cancer cells." (PMID 22745744, 2012). "Loss of CAV1 was frequently observed in various types of malignancies including colon cancer, in which CAV-1 silencing results in activation of multiple survival signals including Src, EGFR, HER2, and the mitogen-activated protein kinase cascade and promotion of cancer transformation and initiation." (PMID 35163100, 2022). "However, in case of colon cancers, the association of Caveolin 1 expression with tumor progression has been variably reported." (PMID 29568375, 2018). "Finally, caveolin-1 expression has been associated with metastasis of tumor cells, including prostate, breast and colon carcinomas." (PMID 22505999, 2012). "Recently, CAV1 was found to be an independent predictor of decreased survival in breast and rectal cancers and was significantly associated with the presence of distant metastasis in colon cancer patients." (PMID 19835603, 2009). "Our previous studies showed that PGE2 can promote COX-2 expression and thereby enhance its own production even in the presence of CAV1/E-cad in colon cancer cells." (PMID 38069269, 2023). "Bioinformatics findings prompted us to further examine the involvement of ezrin and caveolin-1 in mediating vemurafenib resistance in RKO colon cancer cells." (PMID 37629086, 2023). "In colon cancer cells, Caveolin-1 can promote premature senescence through inhibiting Nrf2-dependent signaling." (PMID 35409055, 2022). "Although caveolin-1 function in cancer is controversial, overexpression of caveolin-1 has been reported in colon cancer." (PMID 35377896, 2022). "For HT29(US) colon cancer cells, the expression of CAV1 also resulted in reduced basal respiration and lower respiratory capacity, although the difference was not as pronounced." (PMID 35740528, 2022). "In line with our finding, activation of AMPK by CAV-1 depletion has been also detected in other human colon tumor cells, indicating the activity control of CAV-1 to AMPK is a broad regulation in cancer cells." (PMID 33928090, 2021). "On the one hand, CAV1 protein and mRNA levels are decreased in transformed fibroblasts, in breast, and colon cancer cell lines, and re-expression of CAV1 in colon cancer cells reduces subcutaneous tumor formation in immunosuppressed nude mice." (PMID 32152405, 2020). "This warrants further investigation to determine if CAV-1 is a biomarker of early colon cancer or an indicator of abnormal growth in colon mucosa." (PMID 31889941, 2019). "The expression of CAV1 in colon carcinoma was up-regulated or down-regulated, the results of different studies have been quite different." (PMID 29190968, 2017). "HCT116 colon cancer cells treated for 8 h with 125 μg ml−1 rOly presented more Caveolin-1 (Cav-1) -rich domains than control cells." (PMID 28416764, 2017). "All the anti-neoplastic drugs employed, increased CAV1 expression in the colon cancer cell line HT29(US), but the effect was stronger with the dihydrofolate reductase inhibitor Methotrexate, and the topoisomerase II inhibitor Etoposide." (PMID 29340103, 2017). "All the anti-neoplastic drugs employed, increased CAV1 expression in the colon cancer cell line HT29(US), although increases were most significant for Methotrexate and Etoposide." (PMID 29340103, 2017).
colon carcinoma (continued). "We have previously shown in colon cancer cell lines that increased CAV1 expression arises in conjunction with the development of drug-resistance." (PMID 29340103, 2017). "On the one hand, CAV1 protein and mRNA levels are decreased in transformed fibroblasts and in breast and colon cancer cell lines." (PMID 29340103, 2017). "The 5’ region of the caveolin-1 promoter is enriched in CpG islands that are methylated in breast, lung, ovarian and colon cancer cell lines." (PMID 29340103, 2017). "In colon cancer cells, increased CAV1 expression enhanced migration and invasion in vitro via pathways requiring Src-family kinases, as well as Rac-1 activity." (PMID 29340103, 2017). "In HT29 colon cancer cells, CAV1 expression is silenced by treatment of the cells with butyrate, which induces histone hyperacetylation among other effects." (PMID 29340103, 2017). "HT29(US) human colon cancer cells transduced with either (sh-Scramble) or (sh-Cav1(#5)) containing lentivirus were treated for 48 h either with Methotrexate or Etoposide, washed and then injected intraperitoneally (1x106) into BalbC/NoD/SciD mice." (PMID 29340103, 2017). "Recently, Caveolin-1 has been described as a novel regulator of K-Ras-dependent migration of colon cancer cells." (PMID 27102434, 2016). "High CAV1 expression in advanced colon cancer increased glucose uptake and ATP production by stimulating transcription of glucose transporter 3 (GLUT3, encoded by SLC2A3)." (PMID 27852311, 2016). "For instance, CAV1 expressing colon cancer cells undergo increased glycolysis upon exposure to inhalation anaesthesia (isoflurane), and are thus protected from tumour necrosis factor associated apoptosis." (PMID 27852311, 2016). "For example CAV1 silencing results in a decrease in ERK1/2 phosphorylation in colon cancer and in metastatic lung cancer cells." (PMID 27487136, 2016). "CAV1 promoter hypermethylation has also been reported in sporadic colorectal cancer and re-expression of CAV1 was observed in colon cancer cell lines after 5-AZA treatment." (PMID 26112043, 2015). "Among various prognostic and predictive markers, caveolin 1 (Cav1) has been associated with chemoresistance in various solid tumors, including NSCLC, and with radioresistance in pancreatic and colon cancers." (PMID 26315660, 2015). "Recently, Caveolin-1, as a member of caveolin family, has been reported to act as an anti-apoptotic protein in colon cancer cells by binding to Ku70 and inhibiting Bax-dependent cell death." (PMID 23658834, 2013). "Together, our data indicate that disruption of the interaction between caveolin-1 and Ku70 enhances apoptosis and propose the caveolin-1/Ku70 complex as a novel potential therapeutic target for the treatment of colon cancer." (PMID 22745744, 2012). "To directly address the role of caveolin-1 in chemotherapeutic drug-induced apoptosis in colon cancer cells, we knocked-down caveolin-1 protein expression by siRNA in HCT116 colon cancer cells." (PMID 22745744, 2012). "In this report, we show that knockdown of caveolin-1 protein expression in colon cancer cells enhances apoptosis induced by 5-FU and etoposide." (PMID 22745744, 2012). "We show that knockdown of caveolin-1 protein expression enhances chemotherapeutic drug-induced apoptosis and inhibits long-term survival of colon cancer cells." (PMID 22745744, 2012). "Downregulation of caveolin-1 in the colon carcinoma cells decreases cathepsin B localization to caveolae in parallel with decreases in ECM degradation and cell invasion." (PMID 22093547, 2011). "The role of Cav1 as a negative regulator of raft-dependent uptake of AMF/PGI in tumor cells is supported here by the demonstration that metastatic Cav1-expressing HCT116 colon tumor cells show reduced uptake of AMF/PGI relative to HT29 cells." (PMID 18974847, 2008).